YAP1 (Yes1 associated transcriptional regulator)
Diseases named in the same sentence as YAP1 in open-access papers (continued):
Sharing a sentence is not in itself a finding about the gene and the disease.
ovarian carcinoma (continued). "Therefore, the identification of novel targets with actionable therapeutic drugs specially targeting YAP1 could greatly benefit the clinical outcome of ovarian cancer patients." (PMID 39827153, 2025). "Furthermore, we provide strong evidence that targeting the CK2α-DUB3 axis could be effective in suppressing tumor progression in ovarian cancer and other cancers harboring aberrantly upregulated YAP1." (PMID 39827153, 2025). "Moreover, we discovered that the knockdown of DUB3 in ovarian cancer cells did not affect the transcription of YAP1, while the proteasome inhibition by MG-132 restored the YAP1 protein level caused by DUB3-depletion." (PMID 39827153, 2025). "Additionally, several studies suggest that YAP1 may play a pivotal role in ovarian cancer, where elevated levels of YAP1 correlate with poor patient survival and serve as an independent prognostic marker." (PMID 39827153, 2025). "Furthermore, we demonstrated the therapeutic benefit of targeting YAP1 in ovarian cancer." (PMID 39827153, 2025). "Finally, we probed whether LINC00857 could aggravate ovarian cancer progression and glycolysis via targeting miR‐486‐5p/YAP1 axis through rescue assays." (PMID 32918541, 2020). "Several studies have reported that verteporfin can inhibit YAP1 transcriptional activity thereby leading to tumor growth suppression and sensitization to cytotoxic agents in a variety of tumor types, such as esophageal cancer, rhabdomyosarcoma, ovarian cancer and bladder cancer." (PMID 29228705, 2017). "Furthermore, the results suggest that reducing blood platelet counts or interfering with YAP1 signaling might be an important approach to limit ovarian cancer metastasis." (PMID 28827520, 2017). "Several studies indicated that pharmacological YAP1 inhibitors including verteporfin could suppress tumor growth or sensitize tumor cells to cytotoxics in a variety of tumor types, such as esophageal cancer, rhabdomyosarcoma, ovarian cancer and bladder cancer." (PMID 26716514, 2016). "YAP1 is the transcriptional coactivator in the Hippo signaling pathway and is an oncogene in ovarian cancer by enhancing the transformed phenotype of ovarian cancer cell lines and conferring resistance to chemotherapeutic agents that are commonly used to treat ovarian cancer." (PMID 25180175, 2014). "However, it is also possible that additional mechanisms might be engaged in CK2α-promoted ovarian cancer progression as the reconstitution of YAP1 could not completely restored phenotypical changes caused by targeting CK2α in ovarian cancer cells." (PMID 39827153, 2025). "The depletion of YAP1 in A2780 and SKOV3 cells strongly suppressed cell proliferation and sensitized ovarian cancer cells to cisplatin, while the ectopically overexpressed of YAP1 displayed opposite effects." (PMID 39827153, 2025). "In cellular models encompassing ovarian cancer and glioblastoma, the YAP1-MAML2 fusion generates a chimeric protein that activates YAP1-related transcriptional programs through a TEAD1-dependent mechanism, thereby promoting tumor cell proliferation." (PMID 37849766, 2023). "In ovarian cancer, HBO1 preferentially acetylates histone H4 and is required for the expression of YAP1, an ovarian cancer oncogene and mechano-transductor signaling factor." (PMID 37542030, 2023). "YAP1 was identified as a target of miR-543, and its overexpression was able to reverse the effects of SNHG6 down-regulation on the malignant behaviors of ovarian cancer cells." (PMID 37735423, 2023). "We found a strong correlation between an inactive Hippo gene signature (where YAP1 target gene signatures are expressed), and PVT1 expression in TCGA ovarian cancer datasets." (PMID 35820706, 2022). "Moreover, in ovarian cancer, YAP1 may promote self-renewal of TICs." (PMID 29296212, 2017).
ovarian carcinoma (continued). "To investigate the role of platelets and YAP1 in ovarian cancer metastasis, we injected 2 × 105 HEYA8 human ovarian cancer cells into the left ovary of nude mice and generated thrombocytosis in mice by platelet transfusions twice weekly." (PMID 28827520, 2017). "For instance, YAP1 was shown to affect activities of cisplatin and EGFR inhibitors in ovarian cancer cells." (PMID 26716514, 2016). "However, activating YAP1 in TME and other human ovarian cancer cells by XMU MP1 still needs further investigation." (PMID 39198883, 2024). "Among the ovarian cancer cell lines tested, only SKOV3 reported a 2.2-fold increase in Yap1 expression and a 2.7-fold increase in Taz expression on MS compared to NS scaffolds, supporting mechanosensing-related pathway activation promoted by increased substrate rigidity." (PMID 35269446, 2022). "Pverexpression of YAP1 and under expression of LATS2 in ovary cancer also had poor prognosis." (PMID 36552980, 2022). "In this study, the down-regulation of WT1 increased YAP1 mRNA expression, which may promote the migration and invasion of the SKOV3 ovarian cancer cell line." (PMID 34692659, 2021). "MiR-375 could inhibit the growth and metastasis of ovarian cancer cells, of which the suppressive effect was reversed by MLK7-AS1 lncRNA that indirectly upregulated YAP1 expression." (PMID 33737696, 2021). "For instance, overexpression of YAP1 could contribute to progression and poor prognosis of NSCLC, while knockdown of YAP1 sensitized ovarian cancer cells to cisplatin, erlotinib (EGFR Tyrosine kinase inhibitor) and S12 (survivin inhibitor)." (PMID 26716514, 2016). "Collectively, our results suggest that miR-509-3p-mediated changes in levels of YAP1 and ECM genes impair migration, invasion, and spheroid formation and so may attenuate metastatic progression in advanced stage ovarian cancer." (PMID 27036018, 2016). "Reconstitution of DUB3 WT in endogenous DUB3-deficient cells markedly increased cell proliferation and desensitized cancer cells to cisplatin, whereas reconstitution of the T495A mutant failed to affect YAP1 protein level and displayed a strong suppressive effect on ovarian cancer cells." (PMID 39827153, 2025). "In summary, FLVCR1-AS1/miR-513/YAP1 axis plays a vital role in the cell growth, migration, invasion, tumorigenesis, and EMT in OSC cells, which indicated that FLVCR1-AS1 could act as a potential therapeutic target for human ovarian cancer." (PMID 31412903, 2019). "Furthermore, we have shown that reinstating nuclear YAP1 by specifically inhibiting MST1/2 in TAMs can induce a shift in polarization from M2- to M1-like MФs polarization, offering a viable therapeutic strategy against epithelial ovarian cancer (EOC) peritoneal metastases." (PMID 39198883, 2024). "However, the specific role of YAP1 in ovarian cancer metastasis has not been evaluated so far." (PMID 28827520, 2017).
prostate carcinoma (85 papers, 2016 to 2026). A carcinoma that arises from epithelial cells of the prostate gland. "In prostate cancer, Yes-associated protein 1 (YAP1) has been implicated in maintaining CAF phenotypes that support immune evasion." (PMID 41050070, 2025). "Beyond its oncogenic role, YAP1 has shown predictive value in neoadjuvant settings; its overexpression has been linked to worse outcomes in esophageal and prostate cancers following preoperative treatment." (PMID 40731926, 2025). "The development of protrusions extending from the mid-lobe region of the AGs resembled extra-prostatic extensions observed in human prostate cancer associated with YAP1 overexpression." (PMID 40304035, 2025). "A previous study discovered that yes-associated protein 1 (YAP1), which plays a crucial role in the mammalian hippo signaling pathway and AR, formed a protein complex in the nucleus of prostate cancer cells." (PMID 35756667, 2022). "Yes-associated protein 1 (YAP1) was responsible for converting NFs into CAFs, thus facilitating prostate cancer development." (PMID 33816233, 2021). "The results of our study demonstrate that YAP1 up regulation is linked to prostate cancer aggressiveness independently from established prognostic markers of the disease." (PMID 32488048, 2020). "Through our research, we believe that YAP1 in stromal cells has the potential to serve as a diagnostic marker or therapeutic target for prostate cancer." (PMID 32066485, 2020). "On the contrary, it was previously exhibited that EGR1 could form a complex with a Yes kinase-associated protein 1 (YAP1), thus regulating lipopolysaccharide-induced tissue factor expression in human endothelial cells or cell phenotypes of prostate cancer." (PMID 37188478, 2023). "YAP1 overexpression is linked to poor prognosis in many cancer types, yet its role in prostate cancer is unknown." (PMID 32488048, 2020). "ETS variant transcription factor 1 plays a role in recruiting YAP1 to the promoter region through JMJD2A, leading to changes in histone lysine methylation in human prostate cancer cell lines." (PMID 40066231, 2025). "Overexpression of YAP1 promotes the development of resistance to enzalutamide by enhancing lipid metabolism and cancer stemness in prostate cancer." (PMID 41184230, 2025). "Clinicopathologic studies report elevated nuclear YAP1 in the tumor stroma of more aggressive prostate cancers, including cases with lymph node metastasis or seminal vesicle invasion." (PMID 41514658, 2025). "Collectively, YAP1 influences CAF biology across multiple stages in prostate cancer—from early lineage activation, to maintenance of late myCAFs, to reprogramming of ECM-CAFs toward immune-activating Lym-CAFs." (PMID 41514658, 2025). "ARs have been found to bind with YAP1 in prostate cancer cells and enhance its activity by facilitating its nuclear translocation." (PMID 39397390, 2024). "Previous studies have reported that ARs can bind with YAP1 and promote its nuclear translocation in prostate cancer cells to enhance cell survival." (PMID 39397390, 2024). "In prostate cancer, the YAP1/TEAD complex mediates the occurrence of PNI by activating the transcription of the nerve growth factor NGF." (PMID 38567163, 2024). "YAP1 acts synergistically with AR to shift prostate cancer from androgen-dependent to castration-resistant growth." (PMID 38887275, 2024). "We examined the correlation between the gene expression level of AR and YAP1 in TCGA prostate cancer database (n = 498)." (PMID 39149855, 2024). "Silencing of ANKHD1 leads to the downregulation of YAP1 and decreases prostate cancer cell growth and progression." (PMID 37282627, 2023). "NEK1 haploinsufficient TRAMP mice display reduced YAP1 expression and, if castrated, fail to progress to overt prostate carcinomas, even while displaying reduced E-Cadherin (E-Cad) expression in hyperplastic ductules." (PMID 36979713, 2023).
prostate carcinoma (continued). "YAP1 also regulates the self-renewal property of prostate cancer cells and is negatively regulated by AR via YAP1 promoter methylation." (PMID 37282627, 2023). "ETV1 facilitates the recruitment of JMJD2A to the YAP1 promoter, altering the histone lysine methylation in prostate cancer cells." (PMID 36359354, 2022). "Studies have also found that YAP1 plays a crucial role in the maintenance and expansion of cancer stem cells in breast, lung, and prostate cancer." (PMID 36045416, 2022). "YAP1 was identified as a direct target of miR-375 in prostate cancer, and overexpression of YAP1 abrogated the inhibitory effect of miR-375 on prostate cancer cells." (PMID 35701841, 2022). "It was shown that knockdown of MST1 increased YAP1 nuclear localization and YAP1-AR interactions in prostate cancer cells, which correlated with augmented cell growth independent of androgen exposure, whereas expression of ectopic MST1 had the opposite effect." (PMID 35954292, 2022). "Another mechanism is that high expression of YAP1 in the tumor stromal cells converts normal fibroblasts into CAFs in the TME of prostate cancer." (PMID 36479120, 2022). "YAP1 is overexpressed in many cancers, such as colorectal, lung, liver, ovarian, and prostate cancers, and promotes tumor formation and development." (PMID 34150844, 2021). "YAP1 was upregulated in prostate cancer tissue, and FAP and α-SMA expression were significantly elevated in stromal and epithelial cells with high YAP1 expression levels, demonstrating the association between YAP1 and CAF development." (PMID 33808627, 2021). "The expression of YAP1 is elevated in a number of cancer types, such as liver, lung, colorectal, ovarian, and prostate cancers." (PMID 34150844, 2021). "For instance, MYBL2 was overexpressed in castration-resistant prostate cancer and promoted cell growth and metastatic by promoting YAP1 transcriptional activity." (PMID 34568071, 2021). "This study found that in prostate cancer stromal cells, YAP1, FAP and α-SMA expression levels were significantly elevated compared to those of normal cells." (PMID 32066485, 2020). "We first found that the expression level of YAP1 in the prostate cancer stroma was significantly higher than that in BPH, and the amount of CAF in the prostate cancer stroma increased with the increase in the YAP1 expression level." (PMID 32066485, 2020). "By targeting YAP1, miR-375 was found to inhibit prostate cancer growth, which was shown to be directly repressed by the EMT transcription factor ZEB1." (PMID 32457613, 2020). "The table shows that the expression of YAP1 in the stromal cells of prostate cancer patients is positively correlated with initial PSA." (PMID 32066485, 2020). "In conclusion, high YAP1 protein expression is an independent predictor of unfavourable disease course in prostate cancer." (PMID 32488048, 2020). "This study was undertaken to better understand the role of YAP1 in clinical prostate cancer samples." (PMID 32488048, 2020). "Clinical features have shown that cancer metastasis occurs almost exclusively in prostate cancer patients who have a high expression of YAP1 in stromal cells." (PMID 32066485, 2020). "A study in prostate cancer showed MDSCs were recruited by a YAP1-mediated CXCL5–CXCR2 signaling axis and that the inhibition of YAP led to a decrease in the accumulation of MDSCs." (PMID 33374595, 2020). "YAP1 can convert NFs into CAFs in the tumour microenvironment of PCa, thus promoting the development and metastasis of prostate cancer." (PMID 32066485, 2020). "Our work provided new understandings for the regulation of YAP1 signaling by FER1L4/miR-92a-3p/FBXW7 axis in prostate cancer." (PMID 32140077, 2020). "According to the definition of Gleason Grading formulated by the International Society of Urological Pathology (ISUP) in 2014, we calculated the correlation between YAP1 expression in prostate cancer stromal cells and Gleason Grading." (PMID 32066485, 2020).
prostate carcinoma (continued). "Here, we employed YAP1 immunohistochemistry (IHC) in a tissue microarray containing more than 14,000 prostate cancers with clinical follow-up data." (PMID 32488048, 2020). "In this regard, the research group will continue to conduct in-depth research and strive to use YAP1 as a therapeutic target for prostate cancer." (PMID 32066485, 2020). "The Hippo pathway and it’s downstream regulator YAP1 appear to play a similar important role in prostate cancer as it is known from many other solid cancer types." (PMID 32488048, 2020). "YAP1 can bind to androgen receptor (AR) and affect the proliferation of prostate cancer epithelial cells, thus affecting the progression of prostate cancer." (PMID 32066485, 2020). "This series of experiments aimed to explore how Yes-associated protein 1 (YAP1) regulates the function of stromal cells and how the normal fibroblasts (NFs) convert into CAFs in prostate cancer (PCa)." (PMID 32066485, 2020). "In summary, the data of this study show that YAP1 is a weak, however potentially useful, prognostic parameter in prostate cancer." (PMID 32488048, 2020). "In 25 PCa specimens, the high expression of YAP1 in prostate cancer stromal cells was positively correlated with the Gleason Grading (R = 0.8529, P < 0.0001)." (PMID 32066485, 2020). "Here, we applied YAP1 immunohistochemistry to a tissue microarray containing 17,747 clinical prostate cancer specimens." (PMID 32488048, 2020). "As a positive regulator of FBXW7, we found that FER1L4 decreased stability of YAP1 protein to reduce its expression in prostate cancer cells." (PMID 32140077, 2020). "There is growing evidence that YAP1 migth also play an important role for the biology of both early and late stage prostate cancers." (PMID 32488048, 2020). "In the present studies, we observed that the expression of PDEF in prostate cancer cells results in increased levels of YAP1 and phospho-YAP1 (Ser127) protein and an overall increased ratio of phospho-YAP1 (Ser127)/total YAP1." (PMID 31835563, 2019). "We also observed a gradual decrease in YAP1 mRNA expression during prostate cancer progression (low to high Gleason grade and during metastasis)." (PMID 31835563, 2019). "Our analysis of multiple publicly available clinical cohorts revealed a gradual decrease in YAP1 mRNA expression during prostate cancer progression and metastasis." (PMID 31835563, 2019). "We also observed a decrease in YAP1 mRNA levels in prostate cancer tissues as compared to normal prostate tissues." (PMID 31835563, 2019). "Together, these results suggest that integrity of the YAP1 TEAD-binding domain is require for YAP1 functions in prostate cancer cells renewal." (PMID 29383141, 2017). "Clearly, the exploration of YAP1 function is prostate cancer is in its infancy and additional studies are warranted." (PMID 29383141, 2017). "In prostate cancer, miR-375 is involved in development of chemo-resistance to docetaxel through regulating YAP1 expression." (PMID 28915618, 2017). "Here, we report that YAP1, which is negatively regulated by AR, influences prostate cancer (PCa) cell self-renewal and CRPC development." (PMID 29383141, 2017). "For example, it was shown that YAP-1 binds to EGR-1 in prostate carcinoma cells upon irradiation of the cells." (PMID 27322327, 2016). "In prostate cancer models, pharmacological inhibition of YAP1 was shown to induce phenotypic switching of CAFs from tumor‐promoting to tumor‐suppressive states, consequently enhancing the responsiveness of prostate tumors to immune checkpoint blockade (ICB) therapy." (PMID 41152153, 2025). "Conditioned media from YAP1-high fibroblasts (primary CAFs or YAP1-overexpressing NFs) enhanced proliferation and invasion of multiple prostate cancer cell lines and promoted an EMT-like shift, characterized by reduced E-cadherin and increased N-cadherin and vimentin." (PMID 41514658, 2025).